RPL29P31 (ribosomal protein L29 pseudogene 31)
Synonyms: p17; PERMIT
Gene: Transcribed processed pseudogene on chromosome 17 (43,476,198 to 43,476,665, forward strand). Ensembl gene ENSG00000237888.
Diseases named in the same sentence as RPL29P31 in open-access papers:
RPL29P31 is named in the same sentence as 1 disease in open-access papers, as found by Europe PMC text mining. Sharing a sentence is not in itself a finding about the gene and the disease.
RPL29P31 shares sentences with these, for which no sentence is quoted: amyotrophic lateral sclerosis (1 paper).